NFE2 (nuclear factor, erythroid 2)
Diseases named in the same sentence as NFE2 in open-access papers (continued):
Sharing a sentence is not in itself a finding about the gene and the disease.
cervical cancer (1 paper, 2018). A primary or metastatic malignant neoplasm involving the cervix. "Here we showed that the low expression of NFE2 was associated with better survival, which revealed its similar role in cervical cancer." (PMID 30445744, 2018). "An early report suggested that NFE2 could play a role in megakaryocyte transformation, and that knockdown of NFE2-related factor 2 (NRF2) in cervical cancer could enhance the efficacy of anticancer drugs." (PMID 30445744, 2018).
emphysema (1 paper, 2018). "Low expression of p45 NFE2 in patients with emphysema correlated with a high ECM degradation." (PMID 29476075, 2018). "We isolated ATII cells from control non-smokers, smokers and patients with emphysema to determine the role of NFE2 (nuclear factor, erythroid-derived 2)." (PMID 29476075, 2018). "Therefore, we also wanted to analyze the cross talk between p45 NFE2 and DJ-1 to determine their functional relationship in ATII cells under oxidative stress induced by CS and in emphysema." (PMID 29476075, 2018). "Our results suggest that low p45 NFE2 and DJ-1 interaction in ATII cells in emphysema may contribute to decreased antioxidant defense system in this disease." (PMID 29476075, 2018). "We focused on the role of a nuclear factor, erythroid-derived 2 (NFE2) in ATII cells isolated from patients with emphysema and control non-smokers and smokers." (PMID 29476075, 2018). "We found significantly lower levels of p18 NFE2 and p45 NFE2 in ATII cells in emphysema compared to control non-smokers and smokers by Western blotting." (PMID 29476075, 2018). "We analyzed phosphorylation of tyrosine, serine and threonine residues within p45 NFE2 in ATII cells and lung tissue obtained from non-smokers, smokers and emphysema patients using immunoprecipitation followed by Western blotting." (PMID 29476075, 2018). "However, we observed significantly lower p45 NFE2 and DJ-1 interaction in ATII cells isolated from patients with emphysema compared to control non-smokers or smokers." (PMID 29476075, 2018).
fatty liver disease (1 paper, 2022). A reversible condition wherein large vacuoles of triglyceride fat accumulate in liver cells via the process of steatosis. "Thus, the increased expression of nfe2 might also explain the increased expression of PPAR-γ and SREBP1, leading to fatty liver disease, as observed in IUGR male livers." (PMID 36139771, 2022).
heart failure (1 paper, 2021). Inability of the heart to pump blood at an adequate rate to meet tissue metabolic requirements. "Furthermore, NFE2 is increased in myocardium of anti-miR-132-treated porcine hearts with percutaneous transverse aortic constriction compared with the control group at the 8-week time point, indicating that this could be an effective therapeutic strategy for patients with heart failure." (PMID 34869689, 2021).
Insulin resistance (1 paper, 2019). Increased resistance towards insulin, that is, diminished effectiveness of insulin in reducing blood glucose levels. "Studies have shown that NFE2 improves hepatic insulin sensitivity and whole-body insulin resistance." (PMID 31455213, 2019).
iron deficiency (1 paper, 2013). "In category 2, the genes encoding nuclear factor, erythroid-derived 2 (Nfe2); hemoglobin, theta 1 (Hbq1); erythroid associated factor (Eraf); and 2,3-bisphosphoglycerate mutase (Bpgm) were down-regulated only in the case of short-term iron deficiency." (PMID 23755274, 2013).
Lassa fever (1 paper, 2021). A viral hemorrhagic fever that is caused by the Lassa virus, which is transmitted by contact with infected rodents; it is characterized by fever, headache, malaise, myalgia, and hearing loss. "Indeed, we identified several genes for which the expression correlated with infectious status, such as NFE2, PTP4A3, KCNG2, and a substantial number of genes for which the expression is associated with Lassa fever outcome." (PMID 33398113, 2021).
lung carcinoma (1 paper, 2023). "Lung tissue microarray revealed that 2 of 76 lung cancer patients had genomic rearrangements at the NFE2 locus, and when NFE2 was knocked down, it reduced the proliferation and invasion of H1792 cells." (PMID 36650426, 2023).
periodontitis (1 paper, 2023). An acute or chronic inflammatory process that affects the tissues that surround and support the teeth. "NFE2 plays a critical role in protecting the host from periodontitis tissue damage." (PMID 37495990, 2023).
polycythemia vera (1 paper, 2025). "Even subtle changes in these processes can significantly impact erythroid progression, as evidenced by reduced erythroid maturation upon NFE2 suppression in T56M cells, consistent with a previous report linking elevated NFE2 levels to polycythemia vera." (PMID 40429942, 2025).
postpartum hemorrhage (1 paper, 2022). Hemorrhage defined as a blood loss in excess of 500 mL after vaginal delivery or more than 1000 mL after a cesarean delivery. "Eight genes were associated with hemostatic pathways (SELL, CAPZB, SLC16A3, PDPN, TNFRSF10B, SH2B2, NFE2, and TNFRSF10D), which provided novel insights for the prevention and management of postpartum hemorrhage." (PMID 35836580, 2022).
Sepsis (1 paper, 2023). Sepsis is defined as life-threatening organ dysfunction caused by a dysregulated host response to infection. "Interestingly, two transcriptional factors were identified as up-regulated genes in sepsis from our analysis: NFE2 and ELL2." (PMID 36820206, 2023).
triple-negative breast carcinoma (1 paper, 2022). An invasive breast carcinoma which is negative for expression of estrogen receptor (ER), progesterone receptor (PR), and human epidermal growth factor receptor 2 (HER2). "Recent studies proposed that overexpression of NFE2 could significantly enhance the metastasis capability of triple-negative breast cancer by mimicking the bone microenvironment and activating Wnt pathway." (PMID 35449156, 2022).
cancer (16 papers, 2009 to 2024). A tumor composed of atypical neoplastic, often pleomorphic cells that invade other tissues. "To further support these conclusions, we analyzed the cancer cell line database across all members of the NFE2:MAF family including MAFG, MAFF, MAFK, NFE2L1, and NFE2L2." (PMID 37985752, 2023). "Similarly, NFE2 and TEAD4 are also implicated in various types of cancers and are strongly associated with clinical significance." (PMID 38501838, 2024). "In contrast, H3.1K27M DIPG displayed an enrichment of motifs related to Nuclear Factor Erythroid 2 (NFE2) signaling, particularly involving NFE2L3, which is recognized for its involvement in mediating cancer cell resistance to therapy." (PMID 38791893, 2024). "Conversion of fibroblast growth factor receptor 2b (FGFR2b) to FGFR2c induces EMT and represses nuclear factor-erythroid 2 (NFE2) like basic leucine zipper (bZIP) transcription factor 2 (NRF2)-mediated detoxification of ROS, which leads to the progression of cancer." (PMID 35875696, 2022). "At the same time, there is also evidence that c-MYC levels progressively increase with age, leading to an age-dependent decrease in Nrf2 (nuclear factor erythroid 2 (NFE2)-related factor 2) signaling and adaptive homeostasis, thereby minimizing age-dependent cancer incidence." (PMID 36527013, 2022). "The gene nfe2 is also involved in cancer pathways, cardiovascular disease, and aging; however, none of these pathways were found to be significantly enriched." (PMID 36309536, 2022).
tumor (11 papers, 2012 to 2025). "In order to delineate the molecular mechanism underlying NFE2-mediated enhanced intraosseous tumor formation, we examined the effects of NFE2 expression on in vitro proliferation." (PMID 33081224, 2020). "Collecting the results of our analysis, we hypothesized that NFE2 may be associated with tumor tertiary lymph nodes and circulating tumor cells in LUAD cells." (PMID 36650426, 2023). "Altogether, NFE2 expression can activate the Wnt pathway, which can confer a growth advantage on tumor cells when they grow in a bone cavity with a low oxygen content." (PMID 33081224, 2020). "Consistently, NFE2 proteins were detected at tumor sites arising from intraosseous injection of 4T1.3 cells but not those of 4T1.0 cells." (PMID 33081224, 2020). "When these clones were injected directly into a bone cavity, only the Nfe2-expressing clone formed significantly larger tumor foci compared with a control vector-transfected one together with enhanced NFE2 protein expression at tumor sites." (PMID 33081224, 2020). "Concomitantly, Nfe2 shRNA transduction significantly reduced the tumor growth of 4T1.3 and TS/A.3 clones upon their intraosseous injection with few effects on their tumor formation upon their injection into mammary fat pads." (PMID 33081224, 2020). "We identified ESR1 as a key regulator of establishing a tumor-prone environment and we identified NFE2 as a key regulator of the sustained xenobiotic response." (PMID 24464994, 2014). "Moreover, Nfe2 shRNA treatment reduced tumor formation arising from intraosseous injection of 4T1.3 clone as well as another mouse TNBC-derived TS/A.3 clone with an augmented intraosseous tumor formation ability." (PMID 33081224, 2020). "The analysis revealed most cells in tumor microenvironment including stromal cell expressed EGFR, NFE2, and FSL1 genes while a lower number of cells expressed CDH3, ARL4D, and SH3RF2." (PMID 38172584, 2024). "From the perspective of data mining, this study suggests that MMP12, NFE2, and HOXC8 may be involved in tumor immune regulation and affect immunotherapy." (PMID 36650426, 2023). "Moreover, Nfe2 mRNA was expressed to a larger extent in 4T1.3 obtained from intraosseous tumor sites but not mammary fat pad sites." (PMID 33081224, 2020). "Remarkably, expression levels of key AST factors, IKZF1, NFE2, and IRF8, were significantly enriched in CTCs that were, however, largely absent in primary tumor cells." (PMID 36991428, 2023).
NFE2 also shares sentences with these, for which no sentence is quoted: infection (4 papers); cardiovascular disease (3); blood disease (2); cardiac hypertrophy (2); colon cancer (2); colorectal cancer (2); diabetes (2); erythroleukemia (2); Kawasaki disease (2); neurodegenerative disease (2); ovarian tumor (2); acute monocytic leukemia (1); allergic disease (1); arterial hypertension (1); Arterial thrombosis (1); atherosclerosis (1); bladder cancer (1); bleeding disorders (1); cardiac arrest (1); cholestasis (1); chronic kidney disease (1); colorectal tumours (1); depression (1); fibrosarcoma (1); hematologic diseases (1); hemoglobinopathies (1); Hyperglycemia (1); intestinal tumor (1); ischemic stroke (1); leukocytosis (1).
A further 12 diseases each share a sentence with NFE2 in 1 paper.